CD163 (CD163 molecule)
Diseases named in the same sentence as CD163 in open-access papers (continued):
Sharing a sentence is not in itself a finding about the gene and the disease.
gastric cancer (continued). "In order to examine the role of CD163 in tumor cells, we firstly detected its expression in several gastric cancer cell lines." (PMID 29152078, 2017). "Subsequently, we confirmed overexpression of STAT3 can enhance the CD163 level in gastric cancer cells." (PMID 29152078, 2017). "Results showed a positive relationship with Bmi1 and CD68/CD163 expression in gastric cancer and in colon cancer." (PMID 24312366, 2013). "Additionally, the infiltration of CD163+, CD68+, and CD66b+ cells in gastric cancer tissue was significantly increased and independently associated with gastric cancer prognosis." (PMID 40387965, 2025). "We observed that 5-FU-resistant gastric cancer cells were more effective than 5-FU-sensitive gastric cancer cells in skewing macrophages to M2 polarization, characterized by up-regulated expression of CD163, CD206, IL-10, Arg-1 and VEGF-A and down-regulated expression of CD86, TNF-α and IL-12." (PMID 36151545, 2022). "A recent study noted that the CD163+CD206− TAMs were associated with up-regulated immune signaling and improved survival in gastric cancer, whereas the infiltration of CD68+ only and CD163−CD206+ only TAMs was correlated with a high expression of PD-L1 and tumor immune escape." (PMID 36291863, 2022). "EVs purified from gastric cancer cells, as well as malignant ascitic fluid, differentiated peripheral blood mononuclear cell-derived macrophages into the M2-like phenotype, which was demonstrated by their morphology and expression of CD163/206." (PMID 33509150, 2021). "Similarly, using the fIHC method, higher infiltration with M2 macrophages (CD68+CD163+CD206+) in the stroma was found in gastric carcinoma, and, conversely, higher M1 populations were detected in a tumor-nest area." (PMID 33807310, 2021). "Expression of CD16 and CD163 proteins in HP-positive and HP-negative gastric cancer tissue." (PMID 32332633, 2020). "In addition, the positive expression rates of CD163 protein in HP-positive and HP-negative gastric cancer tissues were 75.38% and 52.00%, separately, and the CD163 protein expression was positively correlated with HP infection (r = 4.556, P = .032)." (PMID 32332633, 2020). "However, the expression of CD163-positive macrophages was significantly up-regulated in gastric cancer tissues than that in margin tissues (P < .05)." (PMID 32332633, 2020). "Similarly, for gastric cancer, there are reports of high CD163 as an indicator of good and bad prognosis." (PMID 32884895, 2020). "Here we show that CD163 is elevated in gastric cancer tissues." (PMID 29152078, 2017). "Here, our data confirms CD163 in gastric cancer has a positive correlation with Tregs (CD4, CD25 and FOXP3), MDSCs (CD33, CD11b and CD14) and Cafs (FAP), indicating CD163 level is an potential index to monitor the status of tumor associated macrophages, Tregs, MDSCs and Cafs in gastric cancer." (PMID 29152078, 2017). "Our data indicate that CD163 may be a potential poor prognostic marker and therapeutic target for gastric cancer." (PMID 29152078, 2017). "In addition, HP infection was obviously related to CD16 protein expression (r = 0.055, P > .05), suggesting that HP infection might promote the development of gastric cancer by affecting CD163 protein expression." (PMID 32332633, 2020). "However, the expression of CD163 in gastric cancer and its regulatory mechanism are still unclear." (PMID 29152078, 2017). "In the study of gastric cancer, the researchers found that CD68+IRF8+M1 TAMs and CD68+CD206+M2 TAMs were closest to the tumor cells, while CD68+CD163+CD206+M2 TAMs were farthest from the tumor cells." (PMID 38279145, 2024). "NACT in gastric cancer induced CD3+ and CD8+ T lymphocytes as well as CD68+ and CD163+ macrophages in the tumor microenvironment in combination with its direct cytotoxic effects." (PMID 34697289, 2021).
gastric cancer (continued). "In a very recent study on dMMR gastric cancer, CD68+CD163− M1-like macrophages were identified as prerequisites for efficient PD-L1/PD-1 blockade because of specific chemokine receptor expression likely activating CTL." (PMID 33870463, 2021). "In conclusion, we combined CD163 expression with TNM staging, age, and gender to construct a nomogram that has the potential to be used as a useful prognostic tool for patients with gastric cancer." (PMID 34458140, 2021). "In the present study, the gastric cancer and margin tissues were collected, and the protein expression of CD16 and CD163 was evaluated and compared." (PMID 32332633, 2020). "A total of 598 surgically resected FFPE primary gastric cancer samples in TMA were assessed for FOXP3, CD163, PD-L1, CD3, and CD8 markers, including 418 males and 180 females." (PMID 31174544, 2019). "RT-qPCR results also showed higher levels of CD163, CD204, CD206, IL-10, and CCL-22 mRNA in peripheral blood-derived macrophages selected from gastric cancer patients than from healthy controls." (PMID 31801938, 2019). "In this study, a total of 598 surgically resected FFPE primary gastric cancer samples were assessed for FOXP3, CD163, CD3, CD8, and PD-L1 markers." (PMID 31174544, 2019). "We also evaluated the correlation between CD163 expression with two key immune checkpoints PD-L1 and CTLA4 in gastric cancer cell lines." (PMID 29152078, 2017). "Gastric cancers were scored as “0” or “1” in each area when the density of CD68+ and CD163+ TAMs was below or above the median value." (PMID 26714314, 2015). "Across all three cancers, nodes in the CD163-high group showed higher SUVmax (all P < 0.001), and the metastasis rate was higher in lung and colorectal but not in stomach cancer." (PMID 41575920, 2026). "For example, the heterogeneity and distribution of TAMs in breast and gastric cancers were explored through fluorescence microimaging and a multiplex panel including markers like CD68, CD163, CD206, IRF8, and PDL1, identifying distinct TAM populations within tumor and adjacent tissues." (PMID 39068459, 2024). "The expression of the M2 markers (CD163) was significantly increased in macrophages incubated with exosomes derived from gastric cells compared to PBS, which proved the effect of exosomes derived from gastric cancer on promoting M2 polarization of macrophages." (PMID 38459513, 2024). "In conclusion, we combined CD163 expression in macrophages, TNM staging, age, and gender to develop a nomogram to predict 3- and 5-year overall survivals after curative resection for gastric cancer." (PMID 34458140, 2021). "Subsequently, IHC and western blot were performed on adjacent normal and tumor tissues extracted from gastric cancer patients to find that Th2 cell markers such as STAT6, GATA3 and the M2 cell polarization marker CD163 were significantly increased in patients with high ITGA5 expression levels." (PMID 33711961, 2021). "Three cases of gastric cancer were examined for CD68 and CD163 expression in the tumor stroma." (PMID 31413815, 2019). "Overlap analysis with genes that co-expressing in 381 gastric cancer tissues and 37 gastric cells demonstrates that various immune related genes such as CCL18, TLR8, C3AR1, CYSLTR2 and CD86 are positively correlated with CD163." (PMID 29152078, 2017). "Finally, we confirm CD163 is a novel target gene of STAT3 (signal transducer and activator of transcription 3) in gastric cancer." (PMID 29152078, 2017). "In multivariate survival analysis, CD163+ TAMs in four combined areas, stromal and epithelial compartments of both tumor center and invasive front were independent prognostic indicator in MSI-high gastric cancers." (PMID 26714314, 2015). "The density of CD68+ or CD163+ TAMs in four different areas (epithelial and stromal compartments of both the tumor center and invasive front) were analyzed in 143 cases of MSI-high advanced gastric cancers using a computerized image analysis system." (PMID 26714314, 2015).
gastric cancer (continued). "Considering the significant roles of CD163 macrophages and CD8 T cells in the tumor microenvironment, BLR and SLR might be potential imaging parameters that could help identify the condition of the tumor immune microenvironment in patients with gastric cancer." (PMID 36983926, 2023). "CD163 was suggested to be significantly correlated with gastric cancer differentiation, invasion depth, lymph node metastasis, and TNM stage (P < .05); while CD16 was not significantly correlated with each clinicopathological factor of gastric cancer (P > .05)." (PMID 32332633, 2020). "Our results indicate that the high density of CD163+ TAMs is an independent prognostic marker heralding prolonged disease-free survival and that the prognostic implication of CD163+ TAMs might be determined by the proportional balance of TAMs and TILs in MSI-high gastric cancers." (PMID 26714314, 2015). "The correlation between HMGB1 and CD68 has been observed in gastric cancer, but the correlation between HMGB1 and CD163 and CD33 has not been reported." (PMID 34257571, 2021). "We observed an increase in MALAT1 expression in gastric cancer tissues compared to normal tissues as well as a moderate positive correlation between CD163 (an indicator of TAM infiltration in tumors) and HIF‐1α gene expression (but not δ‐catenin) in gastric cancer tissues by analyzing TCGA data." (PMID 38639382, 2024). "For instance, in gastric cancer, an analysis of tissues from 56 human cases through multiplex immunohistochemistry (mIHC) identified seven distinct TAM populations based on CD68, CD206, and CD163 expressions, uncovering that not all M2 macrophages directly influence tumor progression." (PMID 39068459, 2024).
atherosclerosis (63 papers, 2012 to 2025). A disease characterized by the build-up of fatty material and calcium deposition in the arterial wall resulting in partial or complete occlusion of the arterial lumen. "Additional biomarkers, including soluble CD14 (sCD14) and soluble CD163 (sCD163), reflect monocyte and macrophage activation, respectively, and have been implicated in the pathogenesis of atherosclerosis and myocardial dysfunction." (PMID 40787484, 2025). "To explore the role of CD163 in the process of VC, we crossed atherosclerosis-prone apolipoprotein E–deficient (ApoE–/–) mice with CD163–/– mice (ApoE–/–CD163–/–) (both on a C57BL/6J background) and compared the features of atherosclerosis with ApoE–/– mice." (PMID 36719758, 2023). "While we were preparing this manuscript, a study reported pathogenic actions of CD163+ macrophages in atherosclerosis where these cells showed activation of HIF1α and VEGF expression and increased vascular permeability and inflammatory cell recruitment." (PMID 30092836, 2018). "Moreover, CD68 and CD163 are two macrophage-associated markers, whose expression levels are associated with adverse outcomes in human atherosclerosis." (PMID 34153003, 2021). "Thus, evaluating the anti-inflammatory cytokines in addition to M2 marker (CD163) in future studies are warranted to provide a better understanding of underlying mechanism of atherosclerosis induce by chronic stress." (PMID 34580342, 2021). "Furthermore, 18F-FDG PET-CT activity was associated with serum levels of soluble CD163 (sCD163), a marker of monocyte/macrophage activation, clearly indicating a role of these cells in accelerated onset of atherosclerosis and CVD in HIV-1 infection." (PMID 31866988, 2019). "Hemoglobin-haptoglobin receptor CD163 positive macrophages were associated with plaque progression, microvascularity, and a high level of HIF1α and VEGF-A expression in atherosclerosis." (PMID 39364414, 2024). "CD163(+) macrophages promote angiogenesis, vascular permeability and inflammation in atherosclerosis via the CD163/HIF1α/VEGF-A pathway." (PMID 36061537, 2022). "A recent study found that CD163+ macrophages promoted plaque angiogenesis, vascular permeability, inflammation, and progression of atherosclerosis, and deletion of CD163 in mice reduced intraplaque neovascularization and plaque progression." (PMID 35221911, 2022). "Some studies have suggested that the scavenger receptor CD163 is upregulated in the presence of pathologies characterised by chronic inflammation such as atherosclerosis and T2D allowing it to neutralise the biological activity of sTWEAK." (PMID 34542797, 2022). "Soluble TWEAK (sTWEAK) decreases while soluble CD163 (sCD163) increases together with the severity of atherosclerosis." (PMID 33854919, 2020). "Generally, the anti-inflammatory macrophage phenotype is considered atheroprotective, although CD163+ macrophages promote atherosclerosis." (PMID 31986489, 2020). "Gaining insights on the role of fifth SRCR domain of CD163 to atherosclerosis and how other diseases, as well as the macrophage polarity, influences the specific uptake of this peptide would be of paramount importance." (PMID 27563889, 2016). "Such probe was able to selectively bind to CD163-expressing macrophages in vitro in human and murine cells, as well as in vivo in a murine model of atherosclerosis." (PMID 26616677, 2015). "Studies performed in atherosclerosis have shown that CD163 expression is increased at inflammatory sites, pointing at the presence of intraplaque hemorrhagic sites or asymptomatic plaques." (PMID 26616677, 2015). "In advanced atherosclerosis model, in ApoE−/− mice, subendothelial infiltration of monocytes/macrophages and platelets was observed, evidenced by a positivity for CD163 and CD61 immunolabelling, in subendothelial space and in lipid accumulation sectors." (PMID 25328689, 2014).
atherosclerosis (continued). "Additionally, the densities of CD20+ B- and CD4+ T-lymphocytes were associated with atherosclerosis- and inflammation-related changes, such as the accumulation of apolipoprotein B-100 and serum amyloid A, and densities of CD68+ and CD163+ macrophages." (PMID 40498464, 2025). "CD163 is expressed exclusively in monocytes (low expression) and macrophages (high expression), is often used as a M2 marker, and is upregulated in several chronic inflammatory diseases such as atherosclerosis, chronic heart failure, and diabetes mellitus." (PMID 40299533, 2025). "On the contrary, increased sCD163 levels lead to decreased TWEAK levels, while CD163 deficiency triggers plaque formation in atherosclerotic mice, suggesting the sCD163/TWEAK plasma ratio as an atherosclerosis marker." (PMID 39451197, 2024). "In addition, CD163+ macrophages also play a crucial role in the progression of atherosclerosis (AS)." (PMID 38321132, 2024). "We hypothesized that dysregulated lipoprotein clearance mediated by CD163+ macrophages might be necessary for atherosclerosis progression among PLWH." (PMID 39483879, 2024). "Serum CD163 was reported to be a biomarker that could be measured in lupus nephritis, accelerated atherosclerosis, and macrophage activation syndrome of SLE." (PMID 35911758, 2022). "Moreover, CD163+ macrophages promote angiogenesis and vascular permeability accompanied by inflammation during atherosclerosis." (PMID 30140291, 2018). "In addition to the function of CD163 in the biology of normal physiology, high expression of CD163 is also involved in disease such as atherosclerosis, acute pancreatitis, diabetes and cancer." (PMID 29152078, 2017). "FH macrophages seem to present lower anti‐inflammatory activity and less capacity of protection against LDL‐mediated oxidative stress due to their lower content in the scavenger receptor CD163, contributing therefore to the premature development of atherosclerosis in these patients." (PMID 27680891, 2017). "Therefore, CTHRSSVVC synthetic peptide sequence is an important candidate as a targeting agent for further development with potential application in molecular imaging and therapy of atherosclerosis and various CD163 positive diseases." (PMID 27563889, 2016). "It is also a potential serum marker for atherosclerosis disease progression besides its role in the clearance of hemoglobin in the form of haptoglobin-hemoglobin complex by the third scavenger receptor cysteine-rich (SRCR) domain of CD163." (PMID 27563889, 2016). "Many of the genes differentially regulated during monocyte-to-macrophage differentiation (downregulated genes include JAK2, STAT6, TLR8, and TLR2, and upregulated genes include VEGFB, TGFB1, FN1, IL-1R2, SCARB1, MSR1, and CD163) have been previously reported in the pathogenesis of atherosclerosis." (PMID 25011540, 2014). "Impaired anti-inflammatory macrophage signaling through a CD163/pAkt/IL-10 axis may thus represent a possible Hp2-2 disease mechanism in atherosclerosis." (PMID 23710416, 2013). "In addition, iron accumulation in the plaques may induce the M (Hb) macrophage differentiation, which expresses CD163 (scavenger receptor cysteine-rich type-1 protein M130) and has, therefore, protective properties in atherosclerosis." (PMID 35459215, 2022). "Expression of CD163 molecules on the intermediate and non-classical monocytes increases in patients with stenosis >70%, which suggests the potential involvement of this molecule in the development of atherosclerosis and associated inflammation." (PMID 33854919, 2020). "Because of the great burden of atherosclerosis in T1DM and the suggested association of TWEAK and CD163 with inflammation and CV disease, we carried out a study to gain some insight into the contribution of TWEAK and CD163 in the pathogenesis of CV disease in T1DM." (PMID 22937125, 2012).
atherosclerosis (continued). "Overall, the expression patterns of CD163 and CD206 in our study highlight the complexity of macrophage polarization in atherosclerosis." (PMID 40496346, 2025). "TNFα is actively involved in the progression of atherosclerosis and influences TWEAK/Fn14/CD163 activity, which through regulatory cascades, leads to worse atherosclerotic outcomes." (PMID 34542797, 2022). "Macrophage-driven angiogenesis is not restricted to tumors; the abundance of the CD163+ macrophages was shown to promote angiogenesis and vascular permeability in other inflammatory conditions, such as atherosclerosis via HIF1α activation and VEGF expression." (PMID 39451197, 2024). "In aged Apoe-/- mice, inhibition of NOX4 activity using GKT137831 significantly reduced macrophage mitochondrial ROS and improved mitochondrial function, resulting in decreased CD68+CD80+ and increased CD163+CD206+ lesion macrophage proportion and attenuated atherosclerosis." (PMID 38975335, 2024). "In our study, CAIX mRNA expression correlated with pro-inflammatory iNOS+ macrophages, but not with CD163+ or Arginase + M2 macrophages in atherosclerosis." (PMID 33432108, 2021). "On the other hand, treatments apt to elicit the expansion of MerTK+ and CD163+ cells (e.g., M2c polarizing agents and IL-4/STAT-6 inhibitors) may help against atherosclerosis progression." (PMID 25972766, 2015). "It has also been shown that sCD163/sTWEAK ratio in peripheral blood is a more sensitive biomarker of subclinical atherosclerosis than sCD163 or sTWEAK alone, indicating that interactions between TWEAK and CD163 might play an important role in vivo." (PMID 23800379, 2013).